IWS1 (interacts with SUPT6H, CTD assembly factor 1)
Description:
Transcription factor which plays a key role in defining the composition of the RNA polymerase II (RNAPII) elongation complex and in modulating the production of mature mRNA transcripts. Acts as an assembly factor to recruit various factors to the RNAPII elongation complex and is recruited to the complex via binding to the transcription elongation factor SUPT6H bound to the C-terminal domain (CTD) of the RNAPII subunit RPB1 (POLR2A). The SUPT6H:IWS1:CTD complex recruits mRNA export factors (ALYREF/THOC4, EXOSC10) as well as histone modifying enzymes (such as SETD2) to ensure proper mRNA splicing, efficient mRNA export and elongation-coupled H3K36 methylation, a signature chromatin mark of active transcription.
Synonyms: DKFZp761G0123; FLJ10006; FLJ14655; FLJ32319
Tractability: PROTAC: ubiquitination databases record sites on it; its protein half-life has been measured.
Gene: Protein-coding gene on chromosome 2 (127,436,207 to 127,526,886, reverse strand). Ensembl gene ENSG00000163166.
Subcellular location: Nucleus
Subcellular location (Human Protein Atlas): Nucleoplasm
Pathways (Reactome):
Gene expression (Transcription): Formation of RNA Pol II elongation complex; RNA Polymerase II Pre-transcription Events; RNA Polymerase II Transcription Elongation
Gene Ontology:
Molecular function: protein binding
Biological process: chromatin remodeling; regulation of mRNA export from nucleus; regulation of mRNA processing; transcription elongation-coupled chromatin remodeling; poly(A)+ mRNA export from nucleus; gene expression
Cellular component: nucleoplasm; nucleus
Genetic constraint (gnomAD): Loss-of-function variants: 12 observed, 51.92 expected, observed/expected ratio (o/e) 0.23, 90% interval 0.15 to 0.37. The upper end of that interval is the gene's LOEUF score, 0.37, which puts it in group 1 of 6, group 1 being the genes least tolerant of losing a copy. Missense variants: 694 observed, 825.76 expected, observed/expected ratio (o/e) 0.84, 90% interval 0.79 to 0.89. Synonymous variants: 255 observed, 284.74 expected, observed/expected ratio (o/e) 0.9, 90% interval 0.81 to 0.99.
Homologues: Orthologues: chimpanzee IWS1 (99% identical), macaque IWS1 (96% identical), dog IWS1 (93% identical), guinea pig IWS1 (91% identical), pig IWS1 (89% identical), rabbit IWS1 (89% identical), mouse Iws1 (84% identical), rat Iws1 (84% identical), tropical clawed frog iws1 (64% identical), Drosophila melanogaster CG9915 (31% identical), Caenorhabditis elegans F13B12.1 (25% identical), Drosophila melanogaster CG12592 (14% identical), and 1 more. Paralogues in human: MDN1 (23% identical), TCHHL1 (11% identical), SAMD15 (9% identical).
Diseases named in the same sentence as IWS1 in open-access papers:
IWS1 is named in the same sentence as 10 diseases in open-access papers, as found by Europe PMC text mining. Sharing a sentence is not in itself a finding about the gene and the disease. The quoted sentences say what the papers report.
breast carcinoma (1 paper, 2018). "In particular, IWS1 seems to be an attractive therapeutic target for lung, skin and breast cancers." (PMID 30208029, 2018).
lung carcinoma (1 paper, 2021). "For instance, IWS1 phosphorylation by AKT in lung cancer was shown to be important for the regulation of RNA processing." (PMID 34685704, 2021).
parasite infection (1 paper, 2023). "Moreover, although wild-type mice showed prolonged survival following IWS1-deficient parasite infection, IFN-γ receptor (IFN-γR)-deficient mice infected with IWS1-deficient parasites succumbed in a similar time period to wild-type parasite-infected wild-type-mice." (PMID 36715543, 2023).
sarcoma (1 paper, 2023). A usually aggressive malignant neoplasm of the soft tissue or bone. "To address the role of IWS1 phosphorylation in sarcoma tumor growth in vivo, we injected 5 × 106 shControl, shIWS1, shIWS1/WT-R or shIWS1/MT-R SW872 cells in immunocompromised NSG mice." (PMID 37237004, 2023). "Targeting IWS1 specifically may circumvent the toxicity of currently available AKT inhibitors, while reducing resistance to chemo and/or radiotherapy by reversing CSC phenotypes in patients with LPS and other forms of sarcoma." (PMID 37237004, 2023).
cancer (3 papers, 2018 to 2023). A tumor composed of atypical neoplastic, often pleomorphic cells that invade other tissues. "Therefore, targeting of IWS1 as a possible therapeutic approach to treat cancer requires caution and further studies." (PMID 30208029, 2018).
tumor (3 papers, 2018 to 2025). "In patients with LPS, IWS1 expression is associated with a reduction in overall survival, and the presence of phosphorylated IWS1 is associated with an increase in the number of tumor recurrences and a shorter time to relapse." (PMID 37237004, 2023). "In addition, a retrospective analysis of patients treated at our center found that increased levels of phosphorylated IWS1 in resected tumors was associated with an increase in the number of tumor recurrences and a shorter disease-free interval in patients with retroperitoneal LPS." (PMID 37237004, 2023). "Lastly, phosphorylation of IWS1 was required for anchorage-independent growth, migration and invasion, and tumor metastases." (PMID 37237004, 2023). "Consistently, we observed that IWS1 phosphorylation promotes tumor growth and lung metastasis in vivo." (PMID 37237004, 2023). "The expression of phosphorylated IWS1 also promotes anchorage-dependent and independent growth, cell migration, invasion, and tumor metastasis." (PMID 37237004, 2023). "Consistent with our in vitro data, the results revealed that the knockdown of IWS1 resulted in reduced tumor growth (tumor volume and weight) and expression of Ki 67, with a parallel reduction in the number of metastatic lung nodules." (PMID 37237004, 2023). "Earlier studies from the Tsichlis lab had shown that the expression of IWS1 varies widely between normal and tumor cells, with the tumor cells expressing significantly higher levels." (PMID 30208029, 2018). "Understanding how the phosphorylation of IWS1 by AKT contributes to LPS tumor biology, could identify novel AKT-dependent targets whose inhibition may materialize the unfulfilled promise of AKT inhibition." (PMID 37237004, 2023). "We found that phosphorylation of the transcription elongation factor, IWS1, by AKT is an important cellular event required for anchorage-independent growth, migration, invasion, and in vivo tumor metastases in preclinical models of human LPS." (PMID 37237004, 2023). "Specifically, phosphorylated IWS1 maintains levels of Nanog, the presence of CD133+ CSCs and EMT status in both cell and xenograft models of LPS and is required for anchorage-independent growth, migration, invasion, and tumor metastases." (PMID 37237004, 2023).
infection (1 paper, 2023). The state of being infected such as from the introduction of a foreign agent such as serum, vaccine, antigenic substance or organism. "However, infection with ROP18-overexpressing IWS1-deficient parasites still resulted in a minor prolonged survival period in mice, indicating the contribution of IWS1-dependent ROP18-independent gene product(s) to the remaining in vivo virulence." (PMID 36715543, 2023).
IWS1 also shares sentences with these, for which no sentence is quoted: hepatocellular carcinoma (1 paper); liposarcoma (1); metastatic tumors (1).